SOX9 (SRY-box transcription factor 9)
Diseases named in the same sentence as SOX9 in open-access papers (continued):
Sharing a sentence is not in itself a finding about the gene and the disease.
infection (continued). "An infection length of 51 days was determined as a balance between animal welfare considerations and likelihood of observing a robust phenotype based on the known time course of SOX9 expression during infection." (PMID 40489560, 2025). "During infection and consistent with other liver injury models, SOX9 expression occurred within activated HSCs in the granuloma scar, cholangiocytes demonstrating ductal hyperplasia, and injured hepatocytes as determined by co-localisation with the hepatocyte specific marker HNF4α." (PMID 40489560, 2025). "(G) Quantification of EdU+Sox9+ cells per 250 μm high infection areas." (PMID 40178080, 2025). "For example, eliminating SOX9 expression in hepatocytes while maintaining SOX9 in HSCs would allow specific focus on how an altered hepatocyte injury response influences hepatic immune modulation and fibrosis during infection." (PMID 40489560, 2025). "Furthermore, the up‐regulation of protein levels of SOX9, collagen II and aggrecan in the H19‐overexpressing cells was rescued following Lenti‐miR‐29b‐3p infection." (PMID 33058414, 2020). "In addition, we performed a WST-1 assay with SOX9 knockout cells after applying a potential new treatment option, infection with an oncolytic virus (T-VEC, approved for melanoma cancer therapy)." (PMID 33076370, 2020). "SOX9 expression was measured using IF during the course of the infection." (PMID 28323899, 2017). "Indeed, we found that co-infection of Nkx3.2ΔC-VP16 with Sox9 completely abolished the ability of Sox9 to inhibit Pax3 and MHC expression." (PMID 22768305, 2012). "To determine the onset time during which Math5/Brn3b-mediated MG transdifferentiation occurs, we immunolabeled retinal flat-mounts of 3.5, 5.5, and 7 days post-infection with antibodies against GFP and Sox9." (PMID 34671605, 2021). "In contrast to Sox9 and Col2a1, siCdc5l mildly increased the Wee1 pre-mRNA splicing efficiency, and this enhancement was cancelled by AAV-CDC5L infection in ATDC5 chondrocytes." (PMID 34298017, 2021). "Six inducing factors, Sry, Sox9, SF1, WT1, GATA4, and Dmrt1, were respectively transduced into mES cells by lentiviral infection according to the experimental design." (PMID 30850007, 2019). "In contrast, infection with the GDF5L373R virus resulted a reduction of inhibitor of differentiation 1 (ID1), which negatively regulates the expression of COL2A1 and SOX9." (PMID 29371961, 2017). "Immunostaining results indicated that either Nkx3.2 or Sox9 infection alone could induce cartilage marker collagen II expression, and that the combination of these two factors had an additive effect, showing a more intense collagen II staining upon Nkx3.2 and Sox9 co-infection." (PMID 22768305, 2012). "SOX9 activation depended on infection because saline treated control and Cebpa mutant lungs did not express SOX9." (PMID 38168395, 2023). "Although no significant changes were detected in the level of Sox9, the level of Acan was significantly increased to 140% or 187% of that in the control by infection with shPax1-a or shPax1-b lentivirus, respectively." (PMID 30872687, 2019). "In the present study, low levels of β-catenin/Wnt signalling at the peak of infection may have been the result of the enhanced expression of AXIN2 and SOX9, observed in crypts at 7 and 14 dpc." (PMID 28323899, 2017). "The infection outcome in various IFN receptor KO’s did not change in NeuN+ or Sox9+ cells." (PMID 39159381, 2024). "In the context of AAV8-Tbg-Cre infection followed by DEN+CCl4, all tumors that appeared to be HCC were uniformly positive for YFP, indicating that they were derived from hepatocytes, although they were also positive for progenitor cell markers, Sox9, Cd133, Cd44 and delta-like 1 homolog." (PMID 36609378, 2023).
infection (continued). "Ectopic expression of miR-146a via infection of primary mouse articular chondrocytes with Lenti-mimic 146a reduced the protein levels of type II collagen (Col2a1) and sex determining region Y (SRY)-box 9 (Sox9) in the absence or presence of pro-inflammatory factors." (PMID 28383548, 2017). "mES cells with lentiviral transduction of all the six factors, Sry, Sox9, SF1, WT1, GATA4, and Dmrt1 (mES+Trans) had a relatively less growth rate as compared to those without infection (group mES+MEF and mES+TM4)." (PMID 30850007, 2019). "By GFP labeling, some of the cells with high GFP expression exhibited a MG-like morphology and co-expressed Sox9 but not the mature RGC marker Rbpms, whereas in retinas without AAV infection, GFP, as a RGC-specific marker expressed from the endogenous Brn3b gene locus, was never found in the MG." (PMID 34671605, 2021). "However, we can essentially rule out this possibility because following infection by GFAP-GFP AAVs, there were no GFP+ cells present in the GCL that co-localized with either Pax2, Sox9, GFAP, or S100β which are astrocyte markers." (PMID 34671605, 2021). "Moreover, at 3.5 days following infection, GFAP-Math5-Brn3b-GFP AAVs did not drive GFP expression in either Sox9-immunoreactive astrocytes or RGCs immunoreactive for Rbpms and Brn3a." (PMID 34671605, 2021).
liver (18 papers, 2012 to 2026). "Previous study demonstrated that SOX9 attenuated acute kidney injury by regulating Wnt/β-catenin signaling." (PMID 36977670, 2023). "Sex determining region Y related high-mobility group box protein 9 (Sox9) is expressed in a subset of hepatocytes, and it is important for chronic liver injury." (PMID 37649095, 2023). "We tested these conditional GEMM of lung ADC to determine if Sox9 expression is an early event downstream of Notch1 signaling." (PMID 25004243, 2014). "To establish the correlation between Sox9 and E-cadherin expression in vivo, we stained the human lung ADC tumors for E-cadherin." (PMID 25004243, 2014). "According to recent researches, upper gastrointestinal (GI) tumors with chromosomal instability are characterized in fragmented genomes and lower GI tumors are enriched in mutations in SOX9 and PCBP1, which reveal the heterogeneity between upper GI tumors and lower GI tumors." (PMID 33552958, 2020). "However, the importance of Sox9 in promoting hepatocyte proliferation in models of chronic liver injury is unknown; thus, more work is needed before strategies that reduce Sox9 expression can be employed in patients with chronic liver diseases." (PMID 30992706, 2019). "Similar to our observations in the Sox9‐CreERT2;Mst4T178E/T178E mice, AOM/DSS‐induced colorectal tumorigenesis was seemingly accelerated in the Sox9‐CreERT2;Ctnnb1T40D/+ mice than in control littermates." (PMID 34240584, 2021). "Moreover, the co‐expression and co‐dependency relationships between SOX9 and TCF7L2 were more pronounced in GBC compared to other gastrointestinal tumors, suggesting a unique interplay between these two TFs in GBC." (PMID 39492805, 2024). "In mammary cell carcinoma, SOX9 is known to be partly responsible for the determination of the stem cell state by inducing epithelial mesenchymal transition (EMT), which is also known to play a decisive role in the genesis of gastrointestinal tumours." (PMID 29703178, 2018).
skeletal dysplasia (8 papers, 2013 to 2026). Any Mendelian diseases that affects growth and development of the skeleton. "According to our findings, ribosome, BMP, ECM, and chromosome segregation related pathways were shown to be altered in SOX9 HI hiPSC-derived chondrocytes, which may help to clarify how skeletal dysplasia manifests in CD patients." (PMID 40025280, 2025). "In summary, the results indicate that the phenotypic consequences of SOX9 mutations are broader than previously reported and include testicular dysgenesis and regression without skeletal dysplasia." (PMID 26740947, 2015). "The results imply that testicular dysgenesis and regression without skeletal dysplasia may be rare manifestations of SOX9 abnormalities." (PMID 26740947, 2015).
adenocarcinoma (4 papers, 2016 to 2024). A common cancer characterized by the presence of malignant glandular cells. "SOX9 was overexpressed in primary adenocarcinomas and particularly in metastases." (PMID 35205666, 2022).
neurodegenerative disease (3 papers, 2020 to 2023). A disorder of the central nervous system characterized by gradual and progressive loss of neural tissue and neurologic function. "It would be, therefore, interesting to further examine the role of SOX9 in other brain diseases including neurodegenerative diseases." (PMID 37065298, 2023).
neurological disorders (3 papers, 2016 to 2023). "Since the function of miR-302 is conserved in mice and humans and Sox9 deletion results in defects in cranial chondrocyte differentiation, we hypothesize that disruption of the miR-302 regulatory axis may underlie some human craniofacial and neurological disorders." (PMID 36724256, 2023). "Five known PKA substrates (FLNA, ACTB, SOX9, MAP4K1 and GBF1) interacted with the domain modules of NBEA and three of these are linked with neurological disorders (FLNA, ACTB, SOX9)." (PMID 26999814, 2016).
CNS tumors (2 papers, 2012 to 2022). "SOX5 and SOX9, as members of the SOX family, are implicated in the development and maintenance of CNS tumors." (PMID 36231068, 2022). "To assess the gene expression profile of hypoxia-induced genes in brain and CNS tumours, we queried the oncomine database for the following genes; HIF1A1, VEGFA, MMP2, NEDD9, SOX4, and SOX9." (PMID 22570651, 2012).
genetic disorder (2 papers, 2013 to 2023). "In developing limbs, a truncated SOX9 mutant interfered with SOX9-mediated Wnt inhibition, resulting in campomelia, a kind of genetic disorder with skeletal malformation." (PMID 37664185, 2023). "Preservation of the SOX9 gene (transcription gene) probably indicates posttranscriptional genetic disorders." (PMID 24102061, 2013).
bacterial infection (1 paper, 2023). "Interestingly, we also observed similar aggregation of MoMFs, SOX9+ hepatocytes, and aHSCs in liver-injury models induced by bacterial infection or ischemia/reperfusion, suggesting such interplay plays an important role in promoting liver necrotic lesion repair in these models." (PMID 37338984, 2023).
connective tissue disorder (1 paper, 2020). A disease involving the connective tissue. "Moreover, from the table of top connective tissue disorders, the network of the term “Abnormality of cartilage tissue” for Epi C vs. Ctr group showed upregulation of collagens, biglycan (BGN), CCN2, and SRY-Box Transcription Factor 9 (SOX9)." (PMID 32575510, 2020).
musculoskeletal disorders (1 paper, 2021). "Similarly, SOX-9 and HHIP loci were found to be associated with DXA-measured bone area.The genetic associations with hip shape in adolescents reported here may be relevant for future risk of age-related musculoskeletal disorders." (PMID 33285254, 2021).
SOX9 also shares sentences with these, for which no sentence is quoted: bone disorder (6 papers); idiopathic pulmonary fibrosis (4); biliary tract cancer (3); type 2 diabetes (3); 22q11.2 deletion syndrome (2); adolescent idiopathic scoliosis (2); biliary atresia (2); Branchio-oculo-facial syndrome (2); congenital heart defect (2); Familial adenomatous polyposis (2); fatty liver (2); Hydroureter (2); hyperandrogenism (2); immune diseases (2); intraductal papillary mucinous neoplasm (2); joint disease (2); knee osteoarthritis (2); lymphoma (2); male infertility (2); MODY (2); Osteochondroma (2); primary immunodeficiency (2); primitive neuroectodermal tumor (2); rhabdomyosarcoma (2); small cell osteosarcomas (2); Stickler syndrome (2); systemic sclerosis (2); teratoma (2); Achilles tendon injuries (1); acute myeloid leukemia (1).
A further 139 diseases each share a sentence with SOX9 in 1 paper.